LEP (leptin)
Diseases named in the same sentence as LEP in open-access papers (continued):
Sharing a sentence is not in itself a finding about the gene and the disease.
Insulin resistance (continued). "After 16 weeks, biometric and glycemic parameters, insulin resistance (IR), hepatic steatosis, oxidative stress markers, and serum leptin, adiponectin, and irisin levels were evaluated." (PMID 40847538, 2025). "Leptin is known to promote inflammation and insulin resistance, while adiponectin exerts protective effects on the liver by enhancing insulin sensitivity and exhibiting anti-inflammatory properties." (PMID 41347218, 2025). "Males also have a higher insulin resistance in both photoperiods, which results in increased compensatory insulin secretion and thus higher leptin production." (PMID 40493338, 2025). "Leptin treatment prevented hepatic fat accumulation and insulin resistance, enhanced insulin and leptin signaling capacity, reduced orexigenic gene expression in the hypothalamus, and promoted browning of retroperitoneal adipose tissue." (PMID 40944384, 2025). "The WD induced a pre‐diabetic state (increased weight, hyperinsulinemia, insulin‐resistance, and hyperleptinemia) and anhedonia, while CS reduced body weight and leptin levels and was anxiogenic." (PMID 40916556, 2025). "Conversely, as pregnancy advances, increasing maternal and placental hormones, including estrogen, progesterone, cortisol, leptin, hPL, and placental growth hormone (PlGH) simultaneously promote a state of insulin resistance." (PMID 40235646, 2025). "Decreased adiponectin levels reduce insulin sensitivity, while increased leptin levels, combined with leptin resistance, fail to counteract insulin resistance effectively." (PMID 39857741, 2025). "Conditions such as insulin resistance in the bladder mucosa, hyperglycemia, and hormonal imbalances (including estrogen and leptin) can alter bladder blood flow and neural regulation." (PMID 40727532, 2025). "These individuals constitute a subgroup of patients with a specific COPD phenotype characterized by an increased leptin–adiponectin imbalance and insulin resistance." (PMID 40868072, 2025). "Insulin resistance can further enhance the pro-inflammatory effects of leptin, exacerbating joint damage." (PMID 41137362, 2025). "Experimental studies in T2DM suggested an improvement in insulin resistance and a suppression of hepatic gluconeogenesis and fasting hyperglycemia in animals receiving leptin replacement therapy." (PMID 38397015, 2024). "Insulin resistance, diabetes mellitus, hypertriglyceridemia, ectopic fat accumulation (e.g., hepatic steatosis), and low leptin level are common characteristics of the disease." (PMID 38952397, 2024). "Obese adolescents with insulin resistance were found to have an inverse relationship with the methylation frequency of the leptin promoter gene, determined by the methylation-specific polymerase chain reaction in DNA obtained from peripheral blood samples." (PMID 38707092, 2024). "Data from recent clinical trials conducted among obese patients with type 2 DM indicated that leptin therapy is ineffective or only marginally effective in improving metabolic abnormalities and insulin resistance." (PMID 38707092, 2024). "In other studies, leptin and adiponectin were positively and negatively correlated with insulin resistance in cats." (PMID 39328456, 2024). "Adipose tissue releases glycerol, NEFAs, hormones (adiponectin, leptin and resistin) and proinflammatory cytokines (adipokines) that are involved in the development of insulin resistance." (PMID 38672494, 2024). "Moreover, leptin-deficient mice presented increased AdipoR1 and AdipoR2 mRNA expression, indicating low circulating adiponectin levels and defective adiponectin signaling, which have been linked to glucose metabolism deregulation, insulin resistance and diabetes." (PMID 39201365, 2024). "As the TyG-WC index was the only insulin surrogate index associated with plasma leptin and LAR after adjustment for BMI, this variable was used to identify an insulin resistance status, defined as a TyG-WC index above the 75th percentile." (PMID 38289144, 2024).
Insulin resistance (continued). "Metabolic and hormonal dysregulation features, including hyperleptinemia, adipocyte leptin hypersecretion, increased insulin resistance, and androgen excess, have been noted in IIH." (PMID 39656493, 2024). "The increased production of adipokines such as leptin or adiponectin leads to metabolic syndrome, insulin resistance, and the development of non-alcoholic fatty liver disease." (PMID 39518404, 2024). "The main outcomes were lipid profiles, anthropometric parameters, insulin resistance, serum glucose levels, leptin, blood pressure, and inflammatory markers." (PMID 39085907, 2024). "paracasei NL41 for 12 weeks reduced insulin resistance, HbA1c, glucagon, leptin, and oxidative stress." (PMID 39125375, 2024). "Elevated CRP impairs leptin function, potentially disrupting satiety signals and promoting metabolic dysregulation, including insulin resistance." (PMID 39770957, 2024). "Apart from the known decrease in insulin levels and insulin resistance, one of the most marked changes was observed for leptin, which decreased with both metformin or lifestyle intervention, with a further improved effect in the combined treatment arm." (PMID 38279016, 2024). "Specifically, microglia are the first to respond to dietary saturated fatty acids, promoting lipid-induced neuronal stress, hypothalamic inflammation, leptin and insulin resistance, and hyperphagia in mice." (PMID 39295865, 2024). "Decreased leptin leads to increased hunger and appetite, especially for energy-dense foods, resulting in a higher likelihood of insulin resistance." (PMID 40302958, 2024). "Adiponectin, leptin and visfatin are adipokines that are arising as potential markers of visceral fat and insulin resistance." (PMID 39175574, 2024). "Leptin also increases LH levels by suppressing neuropeptide Y in the hypothalamus, highlighting the complex interplay of insulin resistance, BMI, and hormonal imbalance in PCOS." (PMID 38737668, 2024). "Recent studies indicate a positive correlation between serum leptin levels and insulin resistance, relatively high leptin levels being correlated with lower insulin sensitivity and hyperinsulinemia." (PMID 39518420, 2024). "Animal studies have also shown that low birth weight mice exhibit different reproductive cycles from normal mice due to leptin, estrogen, and insulin resistance." (PMID 38570862, 2024). "Plasma leptin and LAR were strongly associated with several common insulin resistance surrogates in prepubertal children, most notably with the TyG-WC index." (PMID 38289144, 2024). "We additionally found that ML supplementation significantly increased the serum levels of adiponectin and leptin, two cytokines secreted during adipocyte differentiation, while promoting the expression of PPARγ and inhibiting insulin resistance." (PMID 38672381, 2024). "Ramadan practitioners have altered adipokine patterns typical of insulin resistance, i.e., leptin levels were significantly increased." (PMID 39596418, 2024). "After the investigation, body weight, fasting blood sugar (FBS), irisin, insulin, C‐reactive protein (CRP), interleukin‐6 (IL‐6), interleukin‐1 beta (IL‐1β), leptin, adiponectin, and insulin resistance (IR) were assessed." (PMID 39479712, 2024). "Owing to the opposing effects of leptin and adiponectin on inflammation and insulin resistance, their ratio has been proposed as a marker of adipose tissue dysfunction." (PMID 38672227, 2024). "In summary, adipokine markers contributing to insulin resistance, such as leptin, chemerin, FABP4, and RBP4, are typically elevated in GDM, whereas those contributing to insulin sensitivity, like adiponectin, are reduced in GDM." (PMID 39519218, 2024). "The ability of LAR to discriminate insulin resistance was significant, with similar or even weaker performance compared with isolated plasma leptin." (PMID 38289144, 2024).
Insulin resistance (continued). "Adipokines such as leptin, resistin, and retinol-binding protein 4 increase insulin resistance, whereas adiponectin with anti-inflammatory and antilipogenic effects increases insulin sensitivity." (PMID 39065815, 2024). "The peripheral actions of leptin consist of upregulating proinflammatory cytokines which play an important role in the pathogenesis of type 2 DM and insulin resistance." (PMID 38707092, 2024). "In obese people, a high level of leptin is a result of leptin resistance, similar to insulin resistance." (PMID 38768058, 2024). "Our KetoSAge trial showed lower leptin levels during ketosis, coupled with very low HOMA-IR (no insulin resistance), and the suppression of ketosis increased leptin in lockstep with increasing insulin resistance." (PMID 39062126, 2024). "There was a significant decrease in insulin resistance and leptin (from 18.8 to 12.7 nm/mL, p = 0.05) at six months after the procedure." (PMID 39512985, 2024). "Elevated leptin levels, oxidative stress, inflammation, enhanced insulin resistance, high TSH levels, and increased aromatase activity have been postulated as plausible explanations." (PMID 38465048, 2024). "Inflammatory cytokines, lipid profile, leptin, and insulin resistance were determined from a fasting blood sample." (PMID 38463689, 2024). "Twenty-four months after bariatric surgery, a relevant decline in insulin resistance, leptin levels, inflammation, and oxidative stress was observed." (PMID 39051223, 2024). "Adiposity promotes breast cancer carcinogenesis by (i) stimulating chronic inflammation and (ii) increasing concentrations of testosterone and estrogen, dysregulating leptin, adiponectin, and insulin resistance." (PMID 38530195, 2024). "Once this feedback is disrupted, the antagonistic effect of leptin on insulin production affects signal transduction pathways following insulin–receptor binding, resulting in the development of insulin resistance." (PMID 40302954, 2024). "The lack of leptin action on the hypothalamus causes an increase in appetite, leading to accumulation in adipose tissue, whereas the high level of leptin leads to insulin resistance and glucose intolerance." (PMID 38254811, 2024). "Meanwhile, iron level affects the synthesis and the release of adipokines, including adiponectin and leptin, which have a strong influence on glucose metabolism and insulin resistance." (PMID 38184276, 2024). "Leptin, adiponectin, and resistin are key markers, along with pro-inflammatory cytokines like TNFα, IL-1β, and IL-6, which also play roles in insulin resistance." (PMID 39407941, 2024). "Plasma IL-6, hsCRP, and leptin were positively correlated, whereas plasma adiponectin levels were negatively correlated to markers of adipose tissue insulin resistance." (PMID 38786765, 2024). "Studies have indicated that the development of insulin resistance in the context of sustained intermittent hypoxia is closely tied to the disruption of leptin signaling pathways." (PMID 39006235, 2024). "In hypertensive, insulin-resistant men, fasting plasma leptin concentrations were found to correlate positively with myocardial wall thickness." (PMID 39682585, 2024). "There was a significant increase in blood leptin (‘leptin’ is a key appetite-regulating hormone that normalizes hyperglycemia), insulin resistance reduction, and marginal reduction in inflammation." (PMID 38746941, 2024). "In model 1, plasma leptin and LAR were both significantly associated with all insulin resistance surrogates." (PMID 38289144, 2024). "Adiposity/obesity further increases the risk of cancer-related mortality, and increases levels of inflammatory cytokines, contributes to leptin and adiponectin dysregulation, and increases insulin resistance." (PMID 38530195, 2024).
Insulin resistance (continued). "Shrimp oil improved (p < 0.05) oral glucose tolerance, insulin response, and homeostatic model assessment-estimated insulin resistance index, decreased serum insulin, leptin, HbA1c, and free FAs, while it also increased adiponectin." (PMID 39728129, 2024). "Leptin seems also to play a crucial role in regulating insulin resistance, due to its role in managing the energy balance and fat storage, and is secreted by adipocytes." (PMID 39459443, 2024). "The relationship between leptin and adiponectin, often represented as the leptin to adiponectin (L/A) ratio, plays a significant role in metabolic conditions, such as insulin resistance, and has been suggested as a marker of AT dysfunction and inflammation." (PMID 38786092, 2024). "WAT with a Th1/Th17 polarization induces adipokine dysfunctions, high levels of leptin, insulin resistance, metabolic syndrome, and low levels of adiponectin and resistin." (PMID 39200115, 2024). "The combined effects of insulin resistance and high leptin levels in obese children lead to the premature activation of the HPG axis, disrupting its feedback mechanisms and ultimately resulting in precocious puberty." (PMID 39469573, 2024). "In women with PCOS, leptin levels are elevated due to an increased fat mass, but the body becomes resistant to its effects, similar to insulin resistance." (PMID 39459443, 2024). "Running exercise levels out both the increase in insulin resistance and the increase in leptin level to the level of control animals." (PMID 38791421, 2024). "In summary, serum omentin-1 levels are inversely correlated with BMI, waist circumference, leptin levels, and insulin resistance while positively correlated with adiponectin and HDL levels." (PMID 39409194, 2024). "Neonatal and perinatal action of BPA at estrogen receptors in pancreatic β-cells results in increased insulin synthesis and release, and increased leptin levels, contributing to the eventual development of insulin resistance and impaired glucose tolerance." (PMID 38992091, 2024). "High-fructose diet (HFD) feeding and crocetin treatment in male Wistar rats reduced free fatty acid, rectified dysregulation of mRNA expression of adiponectin, TNF-α, and leptin which was probably related to alleviated insulin resistance." (PMID 38419885, 2024). "Additionally, excessive visceral fat may result in an increased production of adipocytokine (resistin, leptin, adiponectin), which are closely associated with heightened insulin resistance and compromised β-cell efficiency, leading to elevated blood glucose levels." (PMID 39064720, 2024). "In conclusion, in prepubertal Chilean children, plasma leptin and LAR were strongly associated with BMI z-scores and a wide range of insulin resistance surrogates commonly used in epidemiological studies." (PMID 38289144, 2024). "Elevated leptin levels trigger leptin resistance, exacerbate insulin resistance by inflammatory responses, and ultimately lead to cognitive impairment." (PMID 39634656, 2024). "Lipodystrophic patients commonly experience moderate to severe insulin resistance, as leptin and adiponectin are crucial in insulin sensitization." (PMID 38951919, 2024). "It was determined that the body composition components, lipid profile indicators, insulin, glucose, insulin resistance, leptin, ghrelin, irisin, and MDA parameters examined in this study showed positive changes in the intervention groups." (PMID 39768899, 2024). "Attenuating dyslipidemia and resistance to leptin, as well as improving hyperglycemia and insulin resistance, are the other effects of this mineral antioxidant." (PMID 38892574, 2024). "A randomized, double-blind, placebo-controlled trial showed that the administration of L. plantarum LMT1-48 decreased body weight, abdominal visceral fat area, insulin resistance, and leptin levels in overweight subjects by regulating the gut microbiota." (PMID 39323881, 2024).
Insulin resistance (continued). "Among these, leptin, adiponectin, CRP, TNF-α, and resistin are closely associated with the occurrence and development of insulin resistance." (PMID 40302954, 2024). "After adjustments for age, sex, and BMI z-score, plasma leptin and LAR remained strongly associated with the insulin resistance surrogate TyG-WC index." (PMID 38289144, 2024). "Increase in circulating level of leptin can also be attributed to leptin resistance which is usually triggered by systemic and peripheral insulin resistance and these observations are similar to earlier studies including previous studies from our laboratory." (PMID 38561673, 2024). "Encoded by omentin-1 and omentin-2 genes, particularly omentin-1, the main circulating form is positively correlated with adiponectin and high-density lipoprotein levels and negatively correlated with BMI, insulin resistance, triglycerides, and leptin levels." (PMID 38672227, 2024). "This suggests that L. paracasei JY062 can improve leptin and insulin resistance in GLMD mice by increasing the levels of lipocalin and GLP-1 and decreasing the leptin level, which, in turn, improves the disorders of glucolipid metabolism." (PMID 38257160, 2024). "Insulin resistance, breast adipose inflammation, the increased expression of aromatase enzyme, elevated leptin, and the inflammation of breast adipose tissue have all been attributed to obesity-associated post-menopausal breast cancer." (PMID 36672434, 2023). "Negative correlations between LEP and QUICKI and statistical variability in both groups in the case of LEP and QUICKI confirm a highly probable cause-and-effect relationship of the effect of LEP on the level of insulin resistance in people with MetS." (PMID 37109160, 2023). "Insulin resistance reduces adiponectin secretion and clearly increases leptin; the former promotes epithelial cell dysfunction and proteinuria, and the latter promotes renal fibrosis through TGF-β." (PMID 37096235, 2023). "Leptin is a key hormone in the management of hyperphagia, systemic inflammation, overweight conditions, and insulin resistance." (PMID 36833129, 2023). "Leptin and insulin resistance develop in AgRP neurons as well as in peripheral tissues as a result of activation of the c-Jun N-terminal Kinase (JNK)-1 pathway, which also causes AgRP neurons to be activated more frequently." (PMID 36737726, 2023). "Recently, an adiponectin-involving parameter—the leptin/adiponectin ratio—was suggested as a measure reflecting insulin resistance." (PMID 37623858, 2023). "During pregnancy, obese women showed increased insulin resistance, increased leptin and CRP levels, and decreased FT4 and adiponectin levels, which are associated with increased risk of cardio-metabolic pregnancy complications such as GDM and preeclampsia." (PMID 36520252, 2023). "Leptin was reported to decrease β cell apoptosis and lower α cell insulin resistance which usually leads to inhibition of the pathways leading to T2DM." (PMID 36950695, 2023). "By ROC curve analysis, we established a discriminative cutoff value for the onset of insulin resistance (leptin/VAT ratio > 209.4 pg/cm2)." (PMID 37668709, 2023). "A diminished adiponectin/leptin ratio is related to increased insulin resistance, oxidative stress and inflammation." (PMID 37848892, 2023). "Hypothalamic inflammation induces leptin and insulin resistance, disrupting hunger response, lowering energy expenditure, and inducing weight gain in animals." (PMID 36829858, 2023). "A multivariate regressions analysis model was constructed to find significant predictors of both serum total leptin and leptin SR among adiposity measures, insulin resistance indices and lipid markers for patients with T2DM." (PMID 36950695, 2023). "The leptin KO (ob/ob mutant) presented with an obese phenotype as well as corresponding metabolic alterations such as insulin resistance and hyperglycemia." (PMID 37587162, 2023).